AR (androgen receptor)
Diseases named in the same sentence as AR in open-access papers (continued):
Sharing a sentence is not in itself a finding about the gene and the disease.
metastatic prostate carcinoma (continued). "VCaP cells, another metastatic prostate carcinoma-derived cell line, are AR-positive, sensitive to a low level of androgens, and widely used as preclinical CRPC models." (PMID 36428807, 2022). "Therapies directed against the androgen receptor (AR) signaling axis are the mainstay of treatment regime for patients with early- or later-stage metastatic prostate cancer." (PMID 35704598, 2022). "Suppression of androgen receptor (AR) signaling through androgen deprivation therapy (ADT) remains the primary treatment for metastatic prostate cancer (mPCa)." (PMID 36143113, 2022). "This short review work will discuss the current treatment options and recent development of anti-androgen receptor (AR) therapeutic approaches for metastatic prostate cancer." (PMID 35372068, 2022). "Histological findings were compatible with metastatic carcinoma of the prostate, which was immunohistochemically positive for pan-cytokeratin, the androgen receptor, and prostate-specific antigen (PSA)." (PMID 35877211, 2022). "AR enhancer is significantly affected only in the metastatic prostate cancer cohort, which is consistent with the development of the disease." (PMID 36163358, 2022). "Inhibiting the androgen receptor (AR), a ligand-activated transcription factor, with androgen deprivation therapy is a standard-of-care treatment for metastatic prostate cancer." (PMID 36923279, 2022). "Specifically, the possibility of differentiating between AR-dependent and AR-independent metastatic prostate cancer is likely to have profound implications on optimal patient management." (PMID 36439451, 2022). "For metastatic prostate cancer, current standard of treatment consists of a combination of androgen-receptor inhibitors and taxanes, which leaves platinating and alkylating agents open as an alternative treatment option, or as an adjuvant therapy." (PMID 35819193, 2022). "Current therapies for metastatic prostate cancer (PC) primarily target androgen synthesis and/or androgen receptor (AR) signaling (called androgen deprivation therapy, ADT)." (PMID 36358614, 2022). "Enzalutamide, a new generation of AR blockade drug that is FDA-approved for metastatic prostate cancer, which also demonstrated excellent brain penetration capability, provides us a readily testable drug for repurposing in GBM patients." (PMID 34094902, 2021). "The initial treatment for metastatic prostate cancer (PCa) is androgen deprivation therapy (ADT) since the androgen receptor (AR) signaling axis is the major driver of PCa cells." (PMID 34204608, 2021). "AR is a fundamental target for therapy of metastatic prostate cancer, and inhibitors with multiple mechanisms of action and efficacy have been developed." (PMID 33112375, 2021). "The androgen receptor (AR) pathway is a major driver of neoplastic behaviour in the different stages of metastatic prostate cancer (mPCa)." (PMID 34749299, 2021). ": The androgen receptor (AR) pathway is a key driver of neoplastic behaviour in the different stages of metastatic prostate cancer (mPCa)." (PMID 34749299, 2021). "Inhibiting the activity of the ligand-activated transcription factor androgen receptor (AR) is the default first-line treatment for metastatic prostate cancer (CaP)." (PMID 34439101, 2021). "In randomized trials, both chemotherapy and androgen-receptor signaling inhibitors provided significant survival benefits in patients with metastatic prostate cancer (mPCa)." (PMID 33022939, 2020). "Metastatic prostate cancer serves as a relevant example, where the molecular target is the androgen receptor (AR) which functions as a lineage survival factor of luminal prostate epithelial cells." (PMID 32220301, 2020). "Recently, ADT combined with docetaxel, abiraterone, or other androgen receptor axis‐targeted therapies have been considered standard primary treatment options for metastatic prostate cancer patients." (PMID 35475210, 2020).
metastatic prostate carcinoma (continued). "Androgen deprivation therapy to suppress activity of the androgen receptor (AR) is the standard treatment for metastatic prostate cancer (PCa), but tumors invariably recur (castration-resistant prostate cancer, CRPC)." (PMID 32484436, 2020). "A recent study discovered an additional new mechanism of AR deregulation in advanced, metastatic prostate cancer." (PMID 31366128, 2019). "The overwhelmingly oncogenic role of androgen/AR-pathway in supporting the growth and survival of metastatic prostate cancer dictates that androgen/AR-targeted therapy is the best treatment option for patients with the metastatic disease." (PMID 30478344, 2018). "Despite recent advances, the efficacy of androgen/androgen receptor (AR)-targeted therapy remains limited for many patients with metastatic prostate cancer." (PMID 30478344, 2018). "Therapeutic regimes designed to impair AR pathway activity remain the first‐line treatment for metastatic prostate cancer patients." (PMID 29540470, 2018). "The central premise of our study is that the set of miRNAs co-regulated by AR, HOXC6 and NKX2-2 captures the majority of miRNAs associated with metastatic prostate cancer." (PMID 28397780, 2017). "It has been known that hormone deprivation therapy that suppresses androgen receptor (AR) signaling is one of the treatments for metastatic prostate cancer." (PMID 29259714, 2017). "Standard treatment for metastatic prostate cancer (CaP) prevents ligand-activation of androgen receptor (AR)." (PMID 28826481, 2017). "Androgen receptor (AR) and its downstream signaling are fundamental for the development and progression of both localized and advanced metastatic prostate cancer." (PMID 28783103, 2017). "HPGD was highly expressed in androgen receptor (AR)–overexpressing advanced tumors, as well as in metastatic prostate cancers." (PMID 29299133, 2017). "This compensatory interplay is believed to have contributed to the low activity of a combined regimen of everolimus (mTORC1 inhibitor) and bicalutamide (AR antagonist) against metastatic prostate cancer in a phase II trial." (PMID 27557496, 2016). "The goal of this study is to elucidate the functional consequence of induced epithelial plasticity on AR regulation during disease progression to identify factors important for treatment-resistant and metastatic prostate cancer." (PMID 27409172, 2016). "Using this approach, we discovered Dynein Axonemal Heavy Chain 8 (DNAH8) as an AR regulatory factor that is overexpressed in metastatic prostate cancer and predictive of poor prognosis." (PMID 27363033, 2016). "Currently, niclosamide is being evaluated in a clinical trial with enzalutamide in treating patients with androgen receptor positive, castration-resistant, metastatic prostate cancer (NCT02532114)." (PMID 27888804, 2016). "In contrast, ADT inhibiting androgen receptor (AR) signaling by either surgical or medical castration and/or anti-androgen agents is the gold standard for advanced or metastatic prostate cancer." (PMID 25900243, 2015). "Persistent androgen receptor (AR) signaling has been identified as a target for novel therapies and reengages the fact that AR continues to be the primary target responsible for metastatic prostate cancer." (PMID 25062956, 2014). "Together, these findings highlight an inverse correlation between GSK-3/AR and NFκB signaling in patient tumors with potential clinical importance in metastatic prostate cancer." (PMID 25327559, 2014). "The standard treatment for metastatic prostate cancer is surgical or chemical castration which reduces circulating androgens (<50 ng/dL) and suppresses the activity of the androgen receptor (AR)." (PMID 24689036, 2014). "For advanced and metastatic prostate cancer, hormonal therapy that inhibits androgen production and/or blocks androgen receptor (AR) function is the first-line treatment." (PMID 23852643, 2013).
metastatic prostate carcinoma (continued). "Androgen receptor (AR), a member of the superfamily of ligand-activated nuclear receptors, plays a central role in the pathogenesis of primary and metastatic prostate cancer." (PMID 19956729, 2009). "Single amino acid substitutions in the AR ligand binding pocket such as T877A or H874Y, which change the ligand specificities of the AR, have been reported in patients with castration-resistant metastatic prostate cancer." (PMID 18218096, 2008). "The authors identified the androgen receptor (AR) gene among the top genetic mediators, and the AR pathway as a highly enriched pathway for metastatic prostate cancer." (PMID 18691435, 2008). "As a result, treatment for locally advanced and metastatic prostate cancer targets the AR by reducing the levels of androgens or by inhibiting the activation of the AR." (PMID 19675761, 2007). "There are several novel therapeutic approaches in the clinical development of the treatment of metastatic prostate cancer: inhibition of androgen receptor signaling, immune-based treatments, antibody–drug conjugates, epigenetic therapies, and targeting radioligand emitters, among others." (PMID 39796774, 2025). "In the past several years, androgen deprivation therapy (ADT) and next-generation androgen receptor pathway inhibitors (ARPI) when combined with poly (ADP-ribose) polymerase inhibitors (PARPi) have revolutionized the way we treat metastatic prostate cancer (mPCa)." (PMID 41488638, 2025). "Optimal management of metastatic prostate cancer may involve the combination of androgen deprivation therapy (ADT) with novel oral androgen receptor signaling inhibitors (ARSIs) such as abiraterone, enzalutamide, and apalutamide." (PMID 41176642, 2025). "More selective pharmacologic interventions, including AR antagonists like enzalutamide, apalutamide, and darolutamide, directly block AR transcriptional activity and have shown efficacy in metastatic prostate cancer, though their use in melanoma remains investigational." (PMID 40940929, 2025). "Furthermore, while androgen receptor positivity increases in advanced and metastatic prostate cancers, oestrogen receptor ERα expression peaks for high‐grade prostatic intraepithelial neoplasia and is reduced for metastatic prostate cancer." (PMID 38234143, 2024). "However, despite initial success, resistance to AR-directed therapies remains a significant challenge, particularly in metastatic prostate cancer, which remains largely incurable." (PMID 39335158, 2024). "Consequently, androgen receptor blockers like flutamide have been explored for presurgical tumor reduction, drawing parallels to their use in managing metastatic prostate cancers." (PMID 38966478, 2024). "Therefore, drug therapy targeting the AR signaling pathway is a mainstay of treatment for metastatic prostate cancer." (PMID 37118708, 2023). "Most human metastatic prostate cancers exhibit AR-dependent epithelial histology." (PMID 36936664, 2023). "However, despite initial good responses to AR-targeting agents and chemotherapy, the majority of metastatic prostate cancer ultimately develops into castration resistant disease." (PMID 35086953, 2022). "Increases in oncogenic AR activity may be driven by somatic changes that upregulate crucial APUC genes in the metastatic prostate cancer tumors, such as HSD3B2 (1.8-fold increase) and SRD5A1 (2.1-fold increase)." (PMID 37435458, 2022). "Systemic inhibition of AR signalling, either by depleting circulating androgens or by impeding ligand-dependent activation through receptor antagonists, remains the gold-standard treatment for metastatic prostate cancer." (PMID 35568739, 2022). "Noteworthy, EGFR, whose relationship with ECM (and AR) was discussed in the previous section, could also mediate the growth of metastatic prostate cancer but in an AR-independent manner." (PMID 35740556, 2022).
metastatic prostate carcinoma (continued). "This high rate of death may be attributed to continuing synthesis of intra-tumoral androgens and persistent activation of the AR pathway in metastatic prostate cancer despite chemical or surgical castration as well as potent AR inhibition." (PMID 37435458, 2022). "Additionally in metastatic prostate cancer, androgen receptor inhibitors in metastatic prostate cancer, have been shown to be positively correlated with survival." (PMID 35713387, 2022). "AR receptor is highly expressed in both primary and metastatic prostate cancer and patients with such higher AR levels are destined for poor prognosis with early disease recurrence after primary treatment, resistance to androgen deprivation therapy as well as disease progression." (PMID 36551962, 2022). "Survival in men diagnosed with de novo synchronous metastatic prostate cancer has increased following the use of upfront systemic treatment, using chemotherapy and other novel androgen receptor targeted agents, in addition to standard androgen deprivation therapy (ADT)." (PMID 33632752, 2021). "Interestingly, the treatment with betulinic acid of the transgenic TRAP mice model of metastatic prostate cancer resulted in tumor growth inhibition and apoptosis mediated by caspase-3 activation and downregulation of the androgen receptor." (PMID 33920405, 2021). "In addition, an antisense drug targeting all forms of the androgen receptor for the treatment of advanced metastatic prostate cancer has entered a clinical trial (NCT02144051)." (PMID 33353933, 2020). "Understanding how AR-regulated genes promote tumor metastasis could be beneficial for the development of drugs that target critical AR-regulated signaling pathways in lethal metastatic prostate cancer." (PMID 32296610, 2020). "Furthermore, we confirm the central role of AR signaling in mCRPC that mediates its effect through regulators located in non-coding regions and the apparent difference in primary versus metastatic prostate cancers." (PMID 31748536, 2019). "This might be important to consider when stratifying patients into AR- and/or bone-targeting treatments for metastatic prostate cancer." (PMID 29670000, 2018). "Although potent androgen receptor pathway inhibitors (ARPI) improve overall survival of metastatic prostate cancer patients, treatment-induced neuroendocrine prostate cancer (t-NEPC) as a consequence of the selection pressures of ARPI is becoming a more common clinical issue." (PMID 28427194, 2017). "Restoring DAB2IP may also improve castration resistance in addition to radiation resistance as DAB2IP expression inversely correlates with androgen receptor activation status particularly in recurrent or metastatic prostate cancer patients." (PMID 26471467, 2015). "AR amplification was also frequently observed in metastatic prostate cancer." (PMID 26546517, 2015). "Therefore, treatments for patients suffering from locally advanced or metastatic prostate cancer (PC) include the reduction of circulating androgens by surgical or chemical castration as well as the blockade of the androgen receptor (AR) with anti-androgens." (PMID 24887556, 2014). "Furthermore, the “Androgen Receptor Signaling Pathway” seemed to be significantly affected during the transition from primary to more aggressive, metastatic prostate cancer." (PMID 23185449, 2012). "Shortly thereafter, with distinct bioinformatics approaches, two other studies confirmed an attenuated androgen signaling signature in high-grade and metastatic prostate cancer, indicating that down-regulation of the AR pathway, although controversial, is likely to be a true phenomenon." (PMID 21829708, 2011). "The ability to specifically link expression levels to multiple cellular responses will be an important means to examine the functional significance of altered protein expression levels sometimes observed in diseases where AR is moderately over-expressed, such advanced metastatic prostate cancer." (PMID 18978937, 2008).
metastatic prostate carcinoma (continued). "On the basis of our findings, we envision that the strategy of radiation plus AR signaling inhibition (leading to IKKE upregulation) could be effective in treatment-naive metastatic prostate cancer and that radiation in combination with an AR degrader could be one of the viable options." (PMID 41542764, 2026). "Interfering with production of male hormones that activate the androgen receptor (AR), a nuclear hormone receptor that promotes proliferation and luminal differentiation, and interfering with binding of androgens to the AR are the principal treatment strategies for metastatic prostate cancer." (PMID 40454483, 2025). "As ASIs are the backbone systemic treatment in metastatic prostate cancer, and AR gene amplification is a potential resistance mechanism, we hypothesized that depleted AR locus RCFS (enriched for ecDNA) would portend a decreased benefit from treatment with ASIs." (PMID 39020220, 2024). "In conclusion, this extended analysis further reinforces the body of data on the substantial benefits of upfront targeting of the androgen receptor pathway using abiraterone acetate in all men with hormone‐sensitive metastatic prostate cancer, irrespective of metastatic disease risk group." (PMID 35411939, 2022). "By effectively modulating the androgen receptor (AR) and JAK2/STAT3 signaling pathways, it emerges as a compelling targeted therapeutic strategy, making it a promising candidate for treating metastatic prostate cancer." (PMID 39980567, 2025). "While PSMA expression is influenced by androgen receptor pathway inhibitors (ARPI), few studies have examined the specific effects of apalutamide, a widely used ARPI for hormone-sensitive metastatic prostate cancer." (PMID 41353166, 2025). "The PROREPAIR-B study showed that patients with metastatic prostate cancer and germline BRCA2 mutations exhibited a shorter time to developing castration resistance compared with non-carriers, suggesting that tumors in BRCA2 mutation carriers may be less reliant on AR signaling pathways." (PMID 39859392, 2025). "ChIP-seq experiments have shown that AR targets DOCK4, and previous research has demonstrated that DOCK4 is overexpressed in PCa, leading to metastatic prostate cancer." (PMID 37686146, 2023). "To quantify nuclear translocation kinetics of AR proteins in response to treatment, we performed fluorescence recovery after photobleaching (FRAP) analysis in the M12 human metastatic prostate cancer cells stably expressing each GFP-tagged AR protein." (PMID 35848798, 2022). "Multiple treatment options are available for the management of metastatic prostate cancer beyond ADT, including chemotherapy, radiopharmaceuticals, immunotherapy, and agents targeting androgen receptor (AR) signaling." (PMID 34830878, 2021). "ADT has been indicated for the treatment of locally advanced or metastatic prostate cancer and includes luteinizing hormone-releasing hormone (LHRH) agonists and/or androgen receptor (AR) antagonists." (PMID 30557349, 2018). "Increased androgen receptor activity plays a major role in the progression of CRPC formation, which has always been thought to be a major obstacle to treatment of advance/metastatic prostate cancer." (PMID 28549433, 2017). "Nearly all patients with metastatic prostate cancer who are initially treated with ADT will progress to mCRPC, mainly due to reactivation of the AR signaling axis." (PMID 28604629, 2017). "Our integrative analysis of metastatic prostate cancer patient tumors, patient-derived xenografts, and cell models determined that PROX1 is upregulated early in the lineage plasticity continuum and progressively increases as tumors lose AR activity." (PMID 40454483, 2025). "Furthermore, triplet combination therapy, which adds such novel androgen receptor signaling inhibitors to ADT plus docetaxel, has recently been shown to prolong survival in metastatic prostate cancer." (PMID 39516672, 2024).